POMGNT2 (protein O-linked mannose N-acetylglucosaminyltransferase 2 (beta 1,4-))
Description:
O-linked mannose beta-1,4-N-acetylglucosaminyltransferase that transfers UDP-N-acetyl-D-glucosamine to the 4-position of the mannose to generate N-acetyl-D-glucosamine-beta-1,4-O-D-mannosylprotein. Involved in the biosynthesis of the phosphorylated O-mannosyl trisaccharide (N-acetylgalactosamine-beta-3-N-acetylglucosamine-beta-4-(phosphate-6-)mannose), a carbohydrate structure present in alpha-dystroglycan (DAG1), which is required for binding laminin G-like domain-containing extracellular proteins with high affinity.
Synonyms: AGO61; C3orf39; GTDC2; FLJ14566; MDDGA8; MDDGC8
Tractability: Small molecule: a structure with a bound ligand is known. Antibody: UniProt predicts a signal peptide or a membrane-spanning region. PROTAC: ubiquitination databases record sites on it; its protein half-life has been measured.
Gene: Protein-coding gene on chromosome 3 (43,079,229 to 43,106,085, reverse strand). Ensembl gene ENSG00000144647.
Subcellular location: Endoplasmic reticulum membrane
Pathways (Reactome):
Metabolism of proteins: DAG1 core M3 glycosylations
Gene Ontology:
Molecular function: acetylglucosaminyltransferase activity; protein binding; protein O-acetylglucosaminyltransferase activity; glycosyltransferase activity
Biological process: protein O-linked glycosylation; neuron migration; protein O-linked glycosylation via mannose
Cellular component: endoplasmic reticulum; endoplasmic reticulum membrane
Genetic constraint (gnomAD): Loss-of-function variants: 25 observed, 27.3 expected, observed/expected ratio (o/e) 0.92, 90% interval 0.67 to 1.28. The upper end of that interval is the gene's LOEUF score, 1.28, which puts it in group 5 of 6, group 1 being the genes least tolerant of losing a copy. Missense variants: 574 observed, 640.35 expected, observed/expected ratio (o/e) 0.9, 90% interval 0.84 to 0.96. Synonymous variants: 274 observed, 275.95 expected, observed/expected ratio (o/e) 0.99, 90% interval 0.9 to 1.1.
Gene-disease validity (ClinGen):
ClinGen rates the evidence that POMGNT2 causes each of these diseases.
myopathy caused by variation in POMGNT2 (autosomal recessive): Definitive. Any myopathy in which the cause of the disease is a variation in the POMGNT2 gene.
Homologues: Orthologues: chimpanzee POMGNT2 (99% identical), macaque POMGNT2 (99% identical), rabbit POMGNT2 (97% identical), dog POMGNT2 (94% identical), mouse Pomgnt2 (93% identical), rat Pomgnt2 (93% identical), pig POMGNT2 (90% identical), guinea pig POMGNT2 (90% identical), zebrafish pomgnt2 (72% identical), tropical clawed frog pomgnt2 (69% identical). Paralogues in human: EOGT (19% identical).
Diseases named in the same sentence as POMGNT2 in open-access papers:
POMGNT2 is named in the same sentence as 20 diseases in open-access papers, as found by Europe PMC text mining. Sharing a sentence is not in itself a finding about the gene and the disease. The quoted sentences say what the papers report.
dystroglycanopathies (7 papers, 2013 to 2026). "By analyzing the pathological alterations in the early developmental stages of the Pomgnt2-KO mouse brain, we provide deeper insights into how loss of dystroglycan function gives rise to the brain malformations in dystroglycanopathy." (PMID 26060116, 2015). "To clarify the pathogenesis of dystroglycanopathy-associated brain malformation, we analyzed the Pomgnt2-knockout (KO) mouse brain as a disease model by focusing on its early developmental stages." (PMID 26060116, 2015). "Thus, while the loss of POMGNT2 causes perinatal death, Pomgnt2-KO mice could be useful for analyzing the development of the cerebral cortex until birth as a dystroglycanopathy model." (PMID 26060116, 2015). "Therefore, the Pomgnt2-KO mouse could be a useful model to investigate the early phase of dystroglycanopathy-associated brain malformation." (PMID 26060116, 2015). "Our analysis shows that several myopathogenes associated with secondary or tertiary dystroglycanopathies (POMT1, FKTN, POGLUT1, POMK, POMGNT2, ISPD and B4GAT1) are downregulated during satellite cell activation." (PMID 34740639, 2022). "Loss of function (LOF) variants in either POMT1–2 or POMGNT2 cause Walker Warburg Syndrome (WWS), the most severe dystroglycanopathy that is associated with profound brain and eye malformations including cobblestone lissencephaly, hydrocephalus, cerebellar hypoplasia, and retinal defects." (PMID 41533692, 2026). "Using the Pomgnt2-knockout (KO) mouse as a dystroglycanopathy model, we show that breaches of the pial basement membrane appeared at embryonic day 11.5, coinciding with the ectopic clustering of Cajal–Retzius cells and subplate neurons and prior to the migration onset of pyramidal neurons." (PMID 26060116, 2015).
Walker-Warburg syndrome (4 papers, 2015 to 2022). "Multiple single-point mutations in POMGNT2 have been detected in patients with the Walker–Warburg syndrome or limb–girdle muscular dystrophy." (PMID 35444644, 2022).
cobblestone lissencephaly (3 papers, 2021 to 2026). "In mice, cortical migration deficits caused by loss of Pomgnt2 have been well-documented and resemble cobblestone lissencephaly observed in patients with WWS." (PMID 41533692, 2026). "Some of the mutations of POMGnT2 cause severe WWS, but others only result in mild forms of limb-girdle muscular dystrophy, while POMGnT2 knockout mice represent models for cobblestone lissencephaly." (PMID 34582712, 2021).
limb-girdle muscular dystrophy (2 papers, 2021). Limb-girdle muscular dystrophy (LGMD) is a heterogeneous group of muscular dystrophies characterized by proximal weakness affecting the pelvic and shoulder girdles. "Genetic variants of POMGNT2 are associated with limb-girdle muscular dystrophy." (PMID 33829027, 2021).
muscular dystrophies (2 papers, 2021 to 2025). "Although one patient (P8) carried a variant in another gene associated with muscular dystrophy (POMGNT2), it was considered unlikely to be causative." (PMID 41373542, 2025). "In the group of congenital muscular dystrophies, 11 patients received a genetic diagnosis with mutations in the following genes: LAMA2 (three cases); POMGNT1 (one case); COL6 (one case); TTN (one case); GMPPB (one case); POMT2 (one case); POMGNT2 (one case); DMD (one case); and SCGA (one case)." (PMID 34675869, 2021).
cervical adenocarcinoma (1 paper, 2025). An adenocarcinoma arising from the cervical epithelium. "However, POMGNT2 expression has not been studied at the protein level, except for its subcellular distribution in the epithelial cell line HEK293, derived from human embryonic kidney, and HeLa cells, derived from a human cervical adenocarcinoma." (PMID 41301852, 2025).
Duchenne muscular dystrophy (1 paper, 2021). Duchenne muscular dystrophy (DMD) is a neuromuscular disease characterized by rapidly progressive muscle weakness and wasting due to degeneration of skeletal, smooth and cardiac muscle. "Additional variants in aunt were present in DMD (Duchenne muscular dystrophy), POMGNT2 (dystrophy-dystroglycanopathy type A8) that are not involved in cardiac pathology." (PMID 33829027, 2021).
leukemia (1 paper, 2022). A malignant (clonal) hematologic disorder, involving hematopoietic stem cells and characterized by the presence of primitive or atypical myeloid or lymphoid cells in the bone marrow and the blood. "Furthemore, in solid tumors and derived cell lines (i.e., leaving aside leukemia) genes directly involved in the synthesis of core M3 glycan and matriglycan, such as POMGNT2, CRPPA, B4GAT1, LARGE1 and LARGE2 and/or their encoded proteins, are found downregulated." (PMID 36494657, 2022).
tumor (3 papers, 2020 to 2025). "However, whether POMGNT2 plays a vital role in tumor progress remained unclear and needs more efforts in further research." (PMID 33194647, 2020).
POMGNT2 also shares sentences with these, for which no sentence is quoted: congenital muscular dystrophy (2 papers); brain malformation (1); carcinoma (1); cervical cancer (1); glioma (1); hydrops fetalis (1); Lissencephaly (1); muscle-eye-brain disease (1); muscular dystrophy-dystroglycanopathy (1); neuroblastoma (1); promyelocytic leukemia (1).